NKAPD1 (NKAP domain containing 1)
Synonyms: C11orf57; Ahed; FLJ10726
Tractability: PROTAC: UniProt records ubiquitination sites on it.
Gene: Protein-coding gene on chromosome 11 (112,074,086 to 112,085,152, forward strand). Ensembl gene ENSG00000150776.
Subcellular location (Human Protein Atlas): Cytosol
Gene Ontology:
Molecular function: identical protein binding; protein binding
Genetic constraint (gnomAD): Loss-of-function variants: 8 observed, 24.4 expected, observed/expected ratio (o/e) 0.33, 90% interval 0.19 to 0.59. The upper end of that interval is the gene's LOEUF score, 0.59, which puts it in group 2 of 6, group 1 being the genes least tolerant of losing a copy. Missense variants: 289 observed, 330.37 expected, observed/expected ratio (o/e) 0.87, 90% interval 0.79 to 0.96. Synonymous variants: 87 observed, 111.93 expected, observed/expected ratio (o/e) 0.78, 90% interval 0.65 to 0.93.
Homologues: Orthologues: chimpanzee NKAPD1 (99% identical), macaque NKAPD1 (97% identical), pig NKAPD1 (93% identical), dog NKAPD1 (91% identical), rabbit NKAPD1 (91% identical), guinea pig NKAPD1 (89% identical), mouse Nkapd1 (84% identical), rat Nkapd1 (83% identical), tropical clawed frog nkapd1 (51% identical).